LRRK2 (leucine rich repeat kinase 2)
Diseases named in the same sentence as LRRK2 in open-access papers (continued):
Sharing a sentence is not in itself a finding about the gene and the disease.
Parkinson disease (continued). "Thus, a VPS35/LRRK2 axis linked to dominant Parkinson's disease intersects with a pathway mediated by proteins encoded by the recessive Parkinson's disease genes." (PMID 41164908, 2025). "Thus, investigations of LRRK2 are thought to be a platform for understanding the molecular mechanisms that underlie all forms of Parkinson’s." (PMID 40371391, 2025). "Mutations in LRRK2 are known to contribute to dopaminergic neuronal degeneration, and targeted degradation of this protein holds promise for slowing disease progression in genetically defined Parkinson’s patients." (PMID 40574056, 2025). "There have been many reports on the involvement of these autophagy-related mechanisms in neurodegenerative diseases, with Parkinson’s disease (PD) receiving particular attention because of the important roles of several causative and risk genes, including LRRK2." (PMID 39949604, 2025). "A deeper understanding of LRRK2 dimerisation dynamics may also present a therapeutic opportunity to restore the balance between heterodimers and homodimers, potentially modulating disease progression in Parkinson’s patients with LRRK2-linked pathogenesis." (PMID 40949874, 2025). "Longitudinal studies involving larger sample sizes could help determine whether NM-MRI can detect asymptomatic LRRK2 carriers that are at risk of developing overt parkinsonism." (PMID 38729969, 2024). "Of note, LRRK2 was first identified in 2004 as a genetic cause of Parkinson’s disease (PD)." (PMID 38607004, 2024). "Although rare, LRRK2 gene mutations have been termed a potential “Rosetta stone” of parkinsonian disorders as all of the major pathologies related to parkinsonism have been observed, in addition to there being end-stage variability, within families carrying the same pathogenic variant." (PMID 38644975, 2024). "The LRRK2 activating mutation G2019S is the most frequent genetic cause of Parkinson’s disease." (PMID 39705401, 2024). "However, the knockdown of Rab10 in dopaminergic neurons is reported to completely reverse the Parkinson’s related bradykinesia caused by LRRK2-G2019S, indicating that the knockdown of Rab10 can promote behavioral activity." (PMID 39669198, 2024). "The LRRK2 G2019S variant is the most common cause of monogenic Parkinson’s disease." (PMID 38804604, 2024). "The sample included individuals diagnosed with Parkinson disease with pathogenic variants in LRRK2." (PMID 39108519, 2024). "Additionally, autosomal-dominant missense mutations in the LRRK2 gene are the most common genetic predisposition for developing Parkinson's disease." (PMID 38519031, 2024). "Although the prevalence of anxiety and depression in human LRRK2 mutation carriers is similar to that in idiopathic Parkinson’s, it is less clear whether there are sex differences in psychiatric symptoms among manifesting LRRK2G2019S carriers." (PMID 39328984, 2024). "Pathological mutations in the LRRK2 gene are the major genetic cause of Parkinson’s disease (PD)." (PMID 39062128, 2024). "Finally, pathogenic variants in LRRK2 cause dominantly inherited parkinsonism through augmented kinase activity." (PMID 38614108, 2024). "We hypothesized that neural networks carrying the Parkinson’s related LRRK2 G2019S mutation would display inherently different micro-and mesoscale behaviors compared to isogenic healthy controls, both during development and in response to induced perturbation." (PMID 38644975, 2024). "Recent clinical evidence suggests the involvement of glymphatic dysfunction in LRRK2-associated Parkinson’s disease (PD); however, the precise mechanism remains unclear." (PMID 38296953, 2024). "In sporadic and genetic Parkinson's disease cases, a higher brain-age gap was associated with faster decline in episodic memory, and executive and motor function, whereas in asymptomatic LRRK2 cases, a smaller brain-age gap was associated with faster cognitive decline." (PMID 39713239, 2024).
Parkinson disease (continued). "Ten percent of Parkinson’s patients have genetic Parkinson’s in which the cause that triggers the degenerative process is a mutation in a gene such as alpha-synuclein, parkin or LRRK2, among other genes." (PMID 39334784, 2024). "Recent findings indicate that urinary BMP levels are altered in LRRK2 mutation carriers with Parkinson’s disease compared to asymptomatic mutation carriers, supporting the view that altered urinary BMP levels might be reflective of brain pathology." (PMID 38745011, 2024). "PPMI enrolled 184 individuals with LRRK2-associated parkinsonism." (PMID 39108519, 2024). "Effect of Roc T1343A on LRRK2 kinase activity and comparison to Parkinson’s disease (PD) variants." (PMID 39699947, 2024). "However, the dysregulation of leucine-rich repeat kinase 2 (LRRK2) phosphorylation is also another key factor linked to aberrant kinase activity, contributing to neurodegeneration in Parkinsons disease (PD)." (PMID 38960968, 2024). "Besides, the same group reported successful use of CRISPR/Cas9 to introduce the LRRK2 G2019S mutation associated with 1–3% of Parkinson’s disease cases worldwide into marmoset ES cells and iPSC." (PMID 37626830, 2023). "Activating mutations in the leucine-rich repeat kinase 2 (LRRK2) cause Parkinson’s disease." (PMID 37874635, 2023). "Furthermore, Parkinson’s disease-linked mutations in LRRK2 are typically autosomal dominant gain-of-function while those in LRRK1 are autosomal recessive loss-of-function." (PMID 37857821, 2023). "Genetic predisposition also looms as a potential confounding factor; genes like SNCA and LRRK2, previously linked to Parkinson’s disease, could make certain individuals more susceptible to Parkinsonism following mTBI." (PMID 38255648, 2023). "Furthermore, LRRK2 serves as a significant risk factor for both Parkinson’s and Crohn’s disease, conditions associated with impairments in mitophagy and/or mitochondrial health." (PMID 37443813, 2023). "Studies conducted among Asian populations spanning Singapore, Taiwan, and mainland China have established that LRRK2 variants G2385R or R1628P may increase risk for Parkinson disease." (PMID 37445986, 2023). "In addition, a mutation in the LRRK2 N2081D allele results in elevated kinase activity while the LRRK2 R1398H variant increases its enzymatic activity altering LRRK2 functionality in CD and Parkinson’s disease." (PMID 37443813, 2023). "The co-expression of LRRK2 and RAB29 in the substantia nigra is of particular interest, as RAB29 is a candidate risk gene for Parkinson’s, is a putative substrate for LRRK2 kinase activity, and may regulate LRRK2." (PMID 36716346, 2023). "Common and rare variants in the LRRK2 locus are associated with Parkinson’s disease (PD) risk, but the downstream effects of these variants on protein levels remain unknown." (PMID 37422510, 2023). "This knowledge will be helpful to develop therapeutic strategies that target LRRK2, and to better understand how increased LRRK2 activity and lysosomal injury may be linked to Parkinson’s disease." (PMID 37874617, 2023). "Mutations or other factors that activate LRRK2 kinase activity may therefore increase Parkinson’s disease risk through lysosome inhibition." (PMID 37487100, 2023). "But LRRK2 patients are less likely to develop dementia than idiopathic PD (IPD) patients LRRK2-mutation patients showed tremor-predominant parkinsonism, less cognition, and olfactory deficits, as well as more depression, anxiety, and irritability, compared with IPD patients." (PMID 37626558, 2023). "Mutations in the LRRK2 gene constitute a genetic risk factor for both familial and sporadic Parkinson’s disease, suggesting that the LRRK2 protein may play an important role in Parkinson’s." (PMID 36716346, 2023). "LRRK2 gene is highly expressed in immune cells and is biochemically linked with the processes of inflammation, autophagy, and phagocytosis in immune‐related disorders such as Parkinson's disease, IBD, tuberculosis, and leprosy." (PMID 38020709, 2023).
Parkinson disease (continued). "Such activity is increased in harmful versions of LRRK2 linked to Parkinson’s disease." (PMID 37874617, 2023). "LRRK2 activation is linked to Parkinson’s disease (PD) pathogenesis." (PMID 36851782, 2023). "A previous study focused on the relationship between the phosphorylation of Bcl-2 at Thr56 and leucine-rich repeat kinase 2 (LRRK2), a relationship that may be associated with Parkinson’s disease and melanoma." (PMID 38186578, 2023). "Leucine-rich repeat kinase 2 (LRRK2) gene mutations can cause Mendelian Parkinson’s disease (PD)." (PMID 37422510, 2023). "Rare GoF mutations in LRRK2 with high and moderate penetrance and common regulatory variants affecting LRRK2 gene expression significantly increase Parkinson’s disease risk, suggesting that inhibiting LRRK2 kinase activity may be therapeutic." (PMID 36963162, 2023). "Abnormal activation of LRRK2 caused by gene mutation is the main cause of Parkinson’s disease." (PMID 37456776, 2023). "LRRK2 kinase and GRPase inhibitors, such as MLi-2, PF-06447475, GNE-0877, compound 68 and 70, and FX2149, initially developed for treatment of Parkinson’ disease, could be repurposed to treat LRRK2-associated lung cancer." (PMID 36986550, 2023). "One could establish a patient-derived model employing iPSCs from patients with mutations commonly found in Parkinson’s disease, such as LRRK2, PRKN, PINK1, and PRRK2." (PMID 38008744, 2023). "Mutations in LRRK2 are the most common genetic cause of Parkinson’s disease." (PMID 36716346, 2023). "Mutations in LRRK2 have been associated with an increased risk of developing Parkinson’s disease, and some studies have suggested that LRRK2 may also play a role in regulating xenophagy in the gut." (PMID 37443813, 2023). "Furthermore, LRRK2, a well-known regulator in Parkinson’s disease, was recently reported to be downregulated and associated with lung cancer progression, consistent with our findings." (PMID 36499051, 2022). "Rodent studies also showed that LPS-activated microglial cells from transgenic mice overexpressing the Parkinson’s disease-linked Lrrk2 (R1441G) mutation exhibit increased expression and secretion of proinflammatory cytokines compared with wild-type control microglia." (PMID 35324611, 2022). "Mutations in LRRK2 gene are associated with late-onset Parkinson’s disease." (PMID 35336787, 2022). "Mutations in LRRK2 are the most common genetic cause of Parkinson’s disease (PD)." (PMID 35625613, 2022). "Initially, research on the genetics of Parkinson’s disease (PD) concentrated on uncommon family variants of the condition; however, six genes—LRRK2, alpha-synuclein, Parkin, VPS35, DJ-1, and PINK1—have now been conclusively linked to either an autosomal dominant or recessive form of the disease." (PMID 36010353, 2022). "The figures of 40% sensitivity and 80% specificity (the lowest of published studies of alpha-synuclein RT-QuIC) from a study of LRRK2-associated Parkinson’s disease might appear discouraging." (PMID 35813946, 2022). "Additionally, the G2385R allele of the leucine-rich repeat kinase 2 (LRRK2) gene has recently been identified as a frequent genetic mutation that raises the risk of typical Parkinson’s disease exclusively among Asians." (PMID 35743271, 2022). "Interestingly, an LRRK2 mutation (5096A>G) was first found in a German-Canadian family, with a complex clinical spectrum of parkinsonism, dementia, and lower motor neuron signs." (PMID 35893043, 2022). "Additionally, LRRK2 has variants associated with AD and tau pathology is prevalent in individuals carrying a mutation previously associated with Parkinson’s disease." (PMID 35883662, 2022). "In order to investigate the roles of LRRK2, and mutated LRRK2, in the development of Parkinsonism, several rodent models bearing the G2019S mutation have been generated using, for example, bacterial artificial chromosome (BAC) and knock-in (KI) to express human or murine LRRK2 or LRRK2-G2019S." (PMID 36671436, 2022).
Parkinson disease (continued). "LRRK2 toxicity has been mainly explained by an increase in kinase activity, but alternative mechanisms have emerged as underlying causes for Parkinson’s disease, such as the imbalance in LRRK2 homeostasis and the involvement of LRRK2 in aggregation and spreading of α-synuclein toxicity." (PMID 35743250, 2022). "Parkinson’s disease (PD) is conventionally described as an α-synuclein aggregation disorder, defined by Lewy bodies and neurites, and mutations in leucine-rich repeat kinase 2 (LRRK2) are the most common autosomal dominant cause of PD." (PMID 35815712, 2022). "Moreover, PAK6 can bind to LRRK2 (leucine-rich repeat kinase 2), which is a cause of Parkinson’s disease, and is required for LRRK2 to regulate neurite outgrowth." (PMID 33306168, 2022). "BDNF genetic polymorphism may significantly increase the LRRK2-induced risk for Parkinson’s disease patients with an onset age of more than 60 years, implying a synergistic effect between the two genes." (PMID 35743271, 2022). "Pathogenic variants in the LRRK2 gene are a common monogenic cause of Parkinson's disease." (PMID 35708213, 2022). "Activating mutations in the leucine-rich repeat kinase 2 (LRRK2) cause inherited Parkinson’s disease and lead to the phosphorylation of a subset of Rab GTPases, in particular, Rab8A, Rab10, and Rab29 within a conserved residue of the Switch II effector-binding motif." (PMID 36149401, 2022). "Mutations in LRRK2 are the key element of familial Parkinson’s disease." (PMID 37288246, 2022). "Moreover, we identified a significant Parkinson’s disease risk variant enrichment in microglia, showing the strongest association with the Parkinson’s disease gene LRRK2." (PMID 34919646, 2022). "Mutations in LRRK2 increase its kinase activity and cause Parkinson's disease." (PMID 35721463, 2022). "This study show that Parkinson’s disease-linked mutations in LRRK2 cause aberrant brain iron accumulation in vivo and iron dyshomeostasis in vitro, supporting a role of LRRK2 in modulating iron uptake and storage in response to proinflammatory stimuli in microglia." (PMID 34914695, 2021). "Moreover, a comparison of dyskinesia as an investigating level of PD frequency in LRRK2‐associated Parkinsonism and idiopathic PD showed a less frequent format of LRRK2‐linked Parkinsonism." (PMID 34291612, 2021). "We next studied whether mutations equivalent to the common Parkinson's causing LRRK2 mutations would affect LRRK1's ability to phosphorylate Rab7A in cells." (PMID 33459343, 2021). "The monozygotic twin (II-6) may develop Parkinsonism in the future, as patients with LRRK2 variants sometimes develop Parkinsonism later in life." (PMID 33918221, 2021). "Autosomal dominant mutations in LRRK2 that enhance kinase activity cause Parkinson's disease." (PMID 33459343, 2021). "Generally, mutation in LRRK2 gene make the LRRK2-protein overactive in Parkinson’s disease." (PMID 35153741, 2021). "LRRK2 serine/threonine kinase is associated with inherited Parkinson’s disease." (PMID 34580980, 2021). "The LRRK2 gene has rare (p.G2019S) and common risk variants for Parkinson’s disease (PD)." (PMID 32873436, 2021). "Interestingly, closer examination of the differential transcriptomic patterns of the module “LRRK2 in neurons in Parkinson’s disease” showed the inverse relationship between the pathogenic variant and R1398H, wild-type, R1398H-G2019S, or N551K-G2019S variants." (PMID 33466414, 2021). "Mutation in the LRRK2 gene is common in inherited Parkinsonism." (PMID 34502198, 2021). "Lastly, CRISPR application in Parkinson’s includes targeting the LRRK2 gene, linked to familial PD." (PMID 34502143, 2021). "Leucine-rich repeat kinase 2 (LRRK2) is a multidomain protein pertaining to the Roco protein family that has become the topic of an increasing number of studies since it was first associated with Parkinson’s disease (PD)." (PMID 34831434, 2021). "Activating mutations in LRRK2 kinase causes Parkinson’s disease." (PMID 33727250, 2021).
Parkinson disease (continued). "Activating mutations in the LRRK2 kinase cause Parkinson’s disease." (PMID 33727250, 2021). "This will be succeeded by the C. elegans conservation of the RAB29/LRRK2 axis, retromer dysfunction and protein aggregation, pertinently tau and α-synuclein in modelling LRRK2-linked Parkinson’s pathogenesis, with potential implications for modelling the candidate genes of novel GWAS loci." (PMID 34397087, 2021). "Increased oligomerization of mixtures of wild type LRRK2 and disease-associated LRRK2 variants, as would be present in heterozygous patients with Parkinson’s disease, together with the inability of LRRK2 oligomers to sever actin suggest a mechanism for a dominant negative effect." (PMID 34030727, 2021). "We explore what is known about how LRRK2 regulates ciliogenesis, the endosomal–lysosomal system, immune responses and interplay with alpha-synuclein and tau and how this might be linked to Parkinson's' disease." (PMID 32036294, 2020). "Pathogenic LRRK2 mutations lead to overactive kinase activity and so chemically inhibiting this activity could protect against Parkinson's disease." (PMID 32433026, 2020). "Moreover, previous reports have sustained the validity of the LRRK2 WD40 loss-of-function (LRRK2WD40) as an animal model of parkinsonism in D. melanogaster." (PMID 31947539, 2020). "Hyperphosphorylation of Rab8a/10 by mutants of LRRK2, which are inherited in an autosomal dominant fashion, lead to a block in ciliogenesis and aberrant centrosome formation that may be associated with Parkinson disease." (PMID 32969543, 2020). "In addition, LRRK2 is one of the small numbers of proteins shown to cause autosomal Parkinson's disease, mostly upon Gly2019Ser mutation that enhances its kinase activity." (PMID 32589750, 2020). "Hyper-activated LRRK2 is linked to Parkinson’s disease susceptibility and progression." (PMID 33298972, 2020). "Mutations that enhance LRRK2 protein kinase activity cause inherited Parkinson's disease." (PMID 33135724, 2020). "Mutations in Leucine-rich repeat kinase 2 (LRRK2) cause Parkinson’s disease (PD)." (PMID 32375042, 2020). "Furthermore, genetic knockout or inhibition of LRRK2 cause lysosomal abnormalities in rodents and primates, and cells from Parkinson’s patients with LRRK2 mutations also exhibit altered lysosome morphology." (PMID 32256311, 2020). "On the other hand, in experimental models of PD, PCA increased cell viability of G20119S-expressing neuronal cells (a leucine-rich repeat kinase-2-linked Parkinson’s disease model) and decreased the dopaminergic neurodegeneration, oxidative stress and locomotor deficits in a Drosophila." (PMID 32362821, 2020). "Future studies that examine how mutations in LRRK2 affect microglia may help us understand how Parkinson’s disease develops." (PMID 32057291, 2020). "Also, higher grade tau pathology in cortical areas is a prominent feature of LRRK2-associated Parkinson’s disease." (PMID 32269512, 2020). "Mutations in LRRK2 are a common genetic cause of Parkinson’s disease (PD)." (PMID 32733200, 2020). "Inherited mutations in LRRK2 (Leucine-rich-repeat kinase 2) are a common cause of Parkinson’s." (PMID 32321836, 2020). "Mutations in LRRK2 are currently recognized as the most common monogenetic cause of Parkinsonism." (PMID 31664682, 2020). "GSK3β activity is also reported to be associated with LRRK2-G2019S parkinsonism and sporadic PD." (PMID 33231564, 2020). "In humans, LRRK2 is associated with Parkinson’s disease, inflammatory bowel disease, and leprosy." (PMID 32916992, 2020). "LRRK2 is a serine/threonine kinase associated with Parkinson disease." (PMID 32017888, 2020). "Additionally, G2385R polymorphism of the LRRK2 gene which is a known risk factor variant for Parkinson’s Disease in the Han Chinese population, as well as the aldehyde dehydrogenases-2 SNP rs671, which occurs in approximately 45% of the population in Taiwan." (PMID 32887585, 2020).